SP1 (Sp1 transcription factor)
Diseases named in the same sentence as SP1 in open-access papers (continued):
Sharing a sentence is not in itself a finding about the gene and the disease.
tumor (582 papers, 1981 to 2026). "In these malignancies, Sp1 expression is associated with poor clinical prognosis, partly due to its role in inhibiting apoptosis and promoting tumor progression." (PMID 40869407, 2025). "In particular, RELA, a core component of the NF-κB pathway, and SP1, a pleiotropic transcription factor with oncogenic potential, are widely implicated in tumor progression, proliferation, and immune evasion." (PMID 41303462, 2025). "Research has demonstrated a strong association between Sp1-dependent transcription and a subset of features related to tumor cell development and differentiation." (PMID 39228402, 2024). "In this context, a study by Han and Lee has shown the role of Specificity Protein 1 (Sp1), a transcription factor implicated in various aspects of tumor progression." (PMID 37895416, 2023). "In cancer, higher levels of Sp1 are associated with tumor cell survival, proliferation and invasion, and angiogenesis within the tumor." (PMID 37164974, 2023). "The expression levels of Sp1 are associated with tumor grade and M stage, and the expression levels of Sp3 were relevant to tumor grade and TNM stage was observed by the clinicopathological characteristics analysis of PC patients." (PMID 35982909, 2022). "Tumor hypoxia induces HIF1α expression to regulate gene expression and the HIF1α-SP1 interaction also has been reported to associate with gene expression." (PMID 35473752, 2022). "At the same time, the silencing of Sp1 also caused a significant decrease in tumor volume and growth rate (group 1 vs. group 5)." (PMID 34145213, 2021). "IL-10 derived from tumor-associated macrophages (TAMs) increases the expression of specificity protein 1 (Sp1) in LECs in a hypoxic TME." (PMID 36046433, 2021). "Of note, recent reports indicate that non-coding RNA comprised of miRNA and lncRNA are also transcription targets of SP1 as well as encoding genes, suggesting a more complex SP1-centered tumor molecular regulation network than was previously thought." (PMID 33731131, 2021). "CURC has recently shown anti-tumor properties, relying on the inhibition of oncogenic/pro-survival STAT-3 and NF-kB-dependent pathways, of the pro-invasive factor Sp-1, of tumor-associated inflammation." (PMID 31991669, 2020). "Specifically, MMP-9 regulation is positively modulated via the binding activity of transcription factors NF-κB, Sp-1, and AP-1 during tumor-associated migration and invasion." (PMID 32708058, 2020). "In lung tissues, SP1 knockdown was associated to smaller size of 143B tumour, but knockdown of both SP1 and miR‐326 dramatically boosted the growth of 143B tumour." (PMID 32743904, 2020). "Treating mice with ISO at a dose of 150 mg/kg b.w. for six weeks reduced tumour mass, which was associated with the downregulation of Sp1 and Cyclin D1 expression in cancer tissue." (PMID 32726968, 2020). "In the context, Sp1 is positively associated with tumor diameters, whereas Nanog is significantly related with BCLC stage and microvascular invasion." (PMID 27685621, 2016). "Sp1 is positively associated with tumor diameters (P=0.033), whereas Nanog is related with BCLC stage (P=0.040) and microvascular invasion (P=0.045)." (PMID 27685621, 2016). "Transcriptional factor Sp1 plays an important role in tumor-associated angiogenesis due to the regulation of downstream pro-angiogenic genes, such as MMPs and COX-2." (PMID 27806345, 2016).
tumor (continued). "In a parallel experiment, combined knockdown of Sp1, Sp3 and Sp4 or individual knockdown of Sp1 in L3.6pL cells used in an athymic nude mouse xenograft model showed that loss of Sp TFs resulted in a significant inhibition of tumor growth and tumor weights." (PMID 26967243, 2016). "A growing body of evidence indicates that the SP1 protein plays a critical role in many tumor types by regulating expression of the genes associated with growth and metastasis." (PMID 26922862, 2016). "Our previous studies have shown that ARNT cooperated with Sp1 to regulate the expression of genes that were associated with tumor growth." (PMID 25839165, 2015). "The downregulation of CMTM3 in clinical tumor tissues was associated with the methylation of a single CpG site located within the Sp1/Sp3-responsive region of the core promoter." (PMID 24586462, 2014). "Previously, both Sp1 and AP-2 transcription factors were implicated in tumor progression and angiogenesis." (PMID 16872482, 2006). "In summary, this study identified JUN, NFKB1, and SP1 as important biomarkers associated with stem cells and telomere maintenance mechanisms in BC, highlighting their critical roles in tumor progression, alterations in the immune microenvironment, and potential therapeutic targets." (PMID 40666524, 2025). "Furthermore, it promoted SP1-mediated upregulation of bcl-2-associated X protein (Bax), thereby mediating oxaliplatin-induced apoptosis of human tumor cells." (PMID 39228402, 2024). "miR-31-5p and SP1 has been reported to be associated with tumor EMT." (PMID 35473752, 2022). "There is also some evidence supporting the tumor improvement caused by SP1 in HCC." (PMID 35924788, 2022). "In addition, transcription factor specificity protein 1 (SP1)-mediated upregulation of lncRNA LINC00152 via PI3K/AKT pathway was reported to be associated with tumor cell growth and metastasis in GBC." (PMID 34944491, 2021). "Therefore, investigating the actions associated with aberrant activation of Sp1 is important to understanding tumour progression." (PMID 33484377, 2021). "High expression level of SP1 was significantly associated with tumor metastasis and recurrence." (PMID 31892989, 2020). "Both HIF-1α and SP1 were positively associated with tumor metastasis (P<0.001)." (PMID 31892989, 2020). "Furthermore, by regulating genes associated with tumor growth and proliferation, SP1 has been reported to promote tumorigenesis and progression." (PMID 30301189, 2018). "Sp1 is overexpressed in various human tumors, which may upregulate genes associated with tumor development, growth, and metastasis by binding onto promoter sequences." (PMID 22734486, 2012). "This loss of tumor suppressor function will, in the model, result in excess Sp1 production." (PMID 19458766, 2007). "The underlying role and mechanism of Sp1 in tumour progression remain unclear." (PMID 37147632, 2023). "In addition, researchers have reported BeA’s antitumor mechanism to occur through mitochondrial oxidative stress induction, the regulation of SP transcription factor Sp1 (specificity protein 1, a protein encoded by SP1 gene), and the inhibition of proliferative factors mediating tumor cell death." (PMID 36810440, 2023). "Moreover, we found that metastasis-associated LVs could play an active role in tumour metastasis, which was at least partly due to elevated expression of Sp1." (PMID 33484377, 2021). "In this context, SP-1 may have a promising therapeutic value in tumor-associated lymphangiogenesis." (PMID 34572295, 2021).
tumor (continued). "However, the observed positive association suggests that Sp1 and Sp3 have a similar functional role in the context of the tumor microenvironment although other factors, such as the small sample size, could also contribute to these observations." (PMID 23028678, 2012). "Sp1 and c-Myc are well-known oncogenic transcription factors that drive tumor initiation and progression." (PMID 41584043, 2026). "It is held by certain scholars that KP10 restrains tumor angiogenesis via the suppression of Sp1-mediated VEGF expression as well as FAK/Rho GTPase activation." (PMID 41399389, 2026). "The results revealed reduced expression levels of miR-6084 and SP1 in primary tumor tissues from patients with metastatic CRC." (PMID 40493409, 2025). "Our tunable hydrogel platform reveals that multiple tumor-mimicking cues within complex viscoelastic microenvironments reinforce malignant traits, with Sp1 acting as a mechanoresponsive transcription factor that transduces these signals." (PMID 41106320, 2025). "Elevated expression of SP1 promotes tumor progression by regulating cell proliferation, migration, and invasion, and affects the resistance of tumor cells to radio- and chemotherapy." (PMID 41562084, 2025). "SP1 has been shown to be involved in multiple cellular functions by regulating its downstream targets, among which are key oncogenes and tumor suppressors." (PMID 39800760, 2025). "SP1 has been shown to influence genes involved in immune evasion, tumor proliferation, and survival pathways, highlighting its potential as a therapeutic target." (PMID 40817807, 2025). "Studies have revealed that the transcription factor SP1 is a critical binding protein in the PD-L1 promoter region, facilitating PD-L1 overexpression and enhancing tumor cell immune evasion." (PMID 40365340, 2025). "Upregulation of SP1 has been reported as a preceding event for tumor cells to gain chemotherapeutic resistance and metastatic ability in various solid tumor models." (PMID 39800760, 2025). "Sp1 (Specificity Protein 1) is overexpressed in various tumor types and correlates with poor patient survival." (PMID 40758706, 2025). "Sp1 also influences cyclins and cyclin-dependent kinases (CDKs) thereby regulating the cell cycle, sustaining uncontrolled self-renewal, and driving tumor progression." (PMID 40869407, 2025). "Collectively, these data implied that the chronic stress‐induced activation of adrenergic β receptors on tumor cells regulated the content of exosomal SP1." (PMID 39630109, 2025). "PD-L1 and Sp1 interactions are important for tumor immune evasion by reducing T-cell-mediated responses." (PMID 40869407, 2025). "In terms of apoptosis, overexpression of Sp1 can activate anti-apoptotic genes and members of the Bcl-2 family, thereby promoting the survival of tumor cells." (PMID 41560752, 2025). "The synergistic anti-tumor effect of SP1 inhibitor and TEAD inhibitor was also observed by using a newly developed pan-TEAD inhibitor of TEAD auto-palmitoylation, VT107 (Supplementary S4B–F)." (PMID 39875519, 2025). "In vivo experiments in CDX models of luciferase‐labeled FG cells revealed that SP1 and PFKFB4 knockdown also suppressed tumor growth, and the inhibitory effect of SP1 knockdown on tumor growth was rescued by PFKFB4 overexpression." (PMID 40832790, 2025). "Sp1 can promote cells to enter the S phase and drive the proliferation of tumor cells by activating cyclin, proto-oncogene MYC and growth factor receptor IGF1R." (PMID 41560752, 2025). "IHC results showed that the piperlongumine and osimertinib combination effectively downregulated the expression of Ki67, c-Met, and Sp1 in tumor tissues, leading to an extension in the survival time of mice." (PMID 40125551, 2025). "The anti-tumor effects of DCC-2036 on CRC are mediated by its capacity to activate anti-tumor T-cell immunity via the FGR/AKT/SP1/DKK1 axis." (PMID 39788945, 2025).
tumor (continued). "The decrease in SP1 leads to reduced adhesion of tumor cells, highlighting the role of SP1 as a transcription factor in regulating genes involved in cell adhesion." (PMID 41002959, 2025). "Among these, 17 genes were strongly associated with LC, whereas ERBB2, SP1, and ZEB1 were related to other tumor types." (PMID 41226027, 2025). "We found that KLF5 had lower expression in metastatic tumours versus primary tumours and normal tissue, hence potentially acting as a tumour/metastatic suppressor, whereas SP1 displayed the opposite pattern, functioning likely as a tumour/metastatic promoter." (PMID 39748426, 2025). "qRT‐PCR analysis demonstrated that TGF‐β and SP1 expression levels were higher in CRC tissues than in their paired adjacent non‐tumor tissues (n = 192)." (PMID 41017455, 2025). "Recent studies show elevated Sp1 expression associated with lymph node metastasis, advanced TNM (Tumor, Node, Metastasis) stage, and poor prognosis in solid tumors including CRC." (PMID 40869407, 2025). "Specifically, COX-2 inhibition prevents the activation of antioxidant responses mediated by Nrf2 and Sp1, ultimately impairing the redox balance and sensitizing tumor cells to TMZ." (PMID 40298811, 2025). "SP1, as a transcription factor, has been found to have potential as a tumor chemotherapy target gene." (PMID 41372957, 2025). "USP39 regulates the cell cycle and tumor growth of HCC cells by facilitating the deubiquitylation pathway of the SP1 protein, stabilizing its protein level, and prolonging its half-life." (PMID 40990019, 2025). "The acetic acid within the tumor environment can then be taken up by tumor cells and promote the acetylation of transcription factor SP1." (PMID 40399304, 2025). "The highly expressed AURKB in RMS contributes to the apoptosis and ferroptosis resistance of tumor cells through the nucleophosmin 1 (NPM1)/Sp1 transcription factor (SP1)/acyl-CoA synthetase long-chain family member 5 (ACSL5) axis." (PMID 39927464, 2025). "More importantly, single‐cell sequencing data supported that TAX1BP1 is highly expressed exclusively in clusters 3, while lactylation level, VIRMA and SP1 were highly expressed in tumor cells." (PMID 41017455, 2025). "The exosomal lncRNA DOCK9-AS2 enhances EMT and stemness in PTC by modulating the Wnt/β-catenin pathway while interacting with SP1/miR-1972 signaling to support an aggressive tumor phenotype." (PMID 41154428, 2025). "Inhibition or knockdown of SP1 expression levels has been shown to reduce tumor formation, growth, and metastasis." (PMID 40290118, 2025). "SP1 regulates the GC-rich region of the PD-L1 promoter, enhances its transcriptional level, and mediates tumor immune escape." (PMID 40666524, 2025). "Leveraging AI-assisted virtual screening, we identified the natural compound Echinatin as a potent SP1 inhibitor that breaks this resistance circuit and produces marked synergistic anti-tumor activity with Niraparib." (PMID 41304867, 2025). "Specificity protein 1 (Sp1), as a transcription factor, plays a pivotal role in tumorigenesis by regulating the tumor cell cycle, apoptosis, DNA damage response, angiogenesis, and tumor migration and invasion." (PMID 40125551, 2025). "The prohibitive effect of SP1 inhibitor mithramycin A was also confirmed in 4T1 tumor‐bearing mice exposed to chronic stress." (PMID 39630109, 2025). "Chronic stress significantly enhances the secretion of SP1+ tumor‐derived exosomes through the adrenergic β receptor." (PMID 39630109, 2025). "Recent studies have highlighted the role of Sp1 within the tumor microenvironment (TME), particularly its Pro tumorigenic functions." (PMID 40869407, 2025). "Sp1 acts as an oncogenic factor that promotes uncontrolled cell proliferation, tumor survival, progression, and metastasis." (PMID 40869407, 2025).
tumor (continued). "Functionally, the YAP5SA overexpression increased cell proliferation and migration in vitro and promoted tumor growth in vivo; while such effects were significantly abrogated by SP1 knockdown." (PMID 39875519, 2025). "PI3K/AKT is one of these pathways, which has been shown to promote MGMT expression in multiple tumor types by activating transcriptional regulators such as Sp1." (PMID 41300971, 2025). "USP39 stabilizes SP1 protein and prolongs its half-life by promoting its deubiquitylation pathway to regulate cell cycle and tumor growth in HCC cells." (PMID 40990019, 2025). "Previous studies have shown that ionizing radiation affects the occurrence and development of neoplasms by disturbing these molecules, such as SP1, BUB1 and hsa-miR-513b-5p19–25." (PMID 40681531, 2025). "The epigenetic reactivation of EphA7 via dCas9-TET1 reduced tumor growth and enhanced sensitivity to chemo-, radio- and immunotherapy by modulating SP1/DNMT1 and PI3K/AKT signalling." (PMID 41403730, 2025). "Studies have confirmed that Sp1 regulates the expression of c-Met by enhancing its transcription, thereby promoting tumor cell proliferation, migration, and drug resistance, substantially influencing tumorigenesis and progression." (PMID 40125551, 2025). "Nevertheless, YAP/TEAD4/SP1-induced VISTA expression in tumor cells provides a new strategy for targeting VISTA for immune checkpoint therapy." (PMID 39875519, 2025). "For instance, small molecule inhibitors of SP1 have demonstrated significant anti‐tumor efficacy in preclinical studies." (PMID 40817807, 2025). "SP1 knockout in S2-013 cells abrogated the HPS-induced increase in tumour burden, as reflected in tumour weight and volume measurements upon necropsy." (PMID 38429478, 2024). "The majority of research have reported a greater expression level of SP1 in tumor tissues compared to normal or neighboring tissues." (PMID 38228617, 2024). "In the ARSB-treated tumor tissue, free galectin-3 and nuclear Sp1 declined, compared to the control." (PMID 37813168, 2024). "Sp1 belongs to the Sp/Kruppel-like family transcription factors, known to regulate tumor occurrence and development." (PMID 38388534, 2024). "Tumor infiltration results in reduced H3K27me3 and increased H3K27ac modifications, enhanced binding of the transcription activator Sp1 to the Gpr160 gene promoter region, and induction of GPR160 expression." (PMID 39448865, 2024). "Several studies have confirmed that the dysregulation of SP1 contributes to tumor angiogenesis and HCC progression." (PMID 38368381, 2024). "Earlier study has revealed abnormal SP1 protein level in GC, which is related to tumor stage and poor prognosis." (PMID 38356702, 2024). "To validate the results from online database analysis, we examined the expression of PIK3CB and SP1 in a cohort of 40 paired GC and non-tumor tissues by qRT-PCR." (PMID 38356702, 2024). "Results from the TMA cohort also suggested the protein levels of SP1 were upregulated in tumor samples." (PMID 39227375, 2024). "There is a wealth of evidence indicating that various compounds, such as approved drugs for alternative medical conditions, have the capability to downregulate or degrade Sp1, thereby impeding cell/tumor proliferation and invasion and promoting apoptosis." (PMID 39228402, 2024). "We also noted a reduction in tumor stem cell characteristics, accompanied by an increase in H3K9ac, SP1, and MGMT levels, underscoring the potential role of H3K9ac in tumor relapse following TMZ therapy." (PMID 38448295, 2024). "Taken together, the activation of JNK1 is essential for the phosphorylation of Sp1 and for shielding against degradation through the ubiquitin-dependent pathway in tumor cell lines during mitosis." (PMID 39228402, 2024). "Significant differences in DNA methylation level between the patient’s tumor and normal tissues were found for the SP1 gene in all persons (p < 0.05)." (PMID 38540340, 2024).